CIMIP2B (ciliary microtubule inner protein 2B)
Description:
Microtubule inner protein (MIP) part of the dynein-decorated doublet microtubules (DMTs) in cilia axoneme, which is required for motile cilia beating.
Synonyms: FAM166B
Tractability: Small molecule: a structure with a bound ligand is known.
Gene: Protein-coding gene on chromosome 9 (35,561,831 to 35,563,899, reverse strand). Ensembl gene ENSG00000215187.
Subcellular location: Cytoplasm, cytoskeleton, cilium axoneme; Cytoplasm, cytoskeleton, flagellum axoneme
Gene Ontology:
Cellular component: axonemal microtubule; axoneme; cilium; microtubule cytoskeleton
Genetic constraint (gnomAD): Loss-of-function variants: 34 observed, 29.06 expected, observed/expected ratio (o/e) 1.17, 90% interval 0.89 to 1.56. The upper end of that interval is the gene's LOEUF score, 1.56, which puts it in group 6 of 6, group 1 being the genes least tolerant of losing a copy. Missense variants: 369 observed, 340.87 expected, observed/expected ratio (o/e) 1.08, 90% interval 0.99 to 1.18. Synonymous variants: 140 observed, 125.59 expected, observed/expected ratio (o/e) 1.11, 90% interval 0.97 to 1.28.
Homologues: Orthologues: chimpanzee CIMIP2B (95% identical), macaque CIMIP2B (93% identical), pig CIMIP2B (84% identical), dog CIMIP2B (80% identical), rat Cimip2b (76% identical), mouse Cimip2b (62% identical), tropical clawed frog cimip2b (41% identical), zebrafish cimip2b (40% identical), Caenorhabditis elegans F13E9.11 (9% identical). Paralogues in human: TMEM121B (17% identical).
Diseases named in the same sentence as CIMIP2B in open-access papers:
CIMIP2B is named in the same sentence as 12 diseases in open-access papers, as found by Europe PMC text mining. Sharing a sentence is not in itself a finding about the gene and the disease.
CIMIP2B shares sentences with these, for which no sentence is quoted: breast carcinoma (4 papers); cancer (2); lymph node metastasis (2); tumor (2); familial hyperlipidemia (1); germ cell cancer (1); germinoma (1); head and neck cancer (1); lung carcinoma (1); non-small cell lung carcinoma (1); polycystic ovary syndrome (1); schizoaffective disorder (1).